RYR2 (ryanodine receptor 2)
Diseases named in the same sentence as RYR2 in open-access papers (continued):
Sharing a sentence is not in itself a finding about the gene and the disease.
catecholaminergic polymorphic ventricular tachycardia (continued). "Conversely, dysregulation of RyR2 by a number of mechanisms can lead to inappropriate Ca2+ release during diastole (“RyR2 leak”), which is associated with several cardiac diseases including catecholaminergic polymorphic ventricular tachycardia, atrial fibrillation, and heart failure." (PMID 34200203, 2021). "Besides ACM, mutations in RYR2 have been linked with catecholaminergic polymorphic ventricular tachycardia (CPVT, MIM #604,772)." (PMID 34478111, 2021). "Mutations in RYR2 could induce bradycardia in patients with catecholaminergic polymorphic ventricular tachycardia (CPTV)." (PMID 33914752, 2021). "Catecholaminergic polymorphic ventricular tachycardia (CPVT) is a rare inherited cardiac disease predominantly caused by an autosomal dominant mutation occurring in the gene encoding the cardiac ryanodine receptor (RYR2)." (PMID 32575374, 2020). "Dysfunction of systolic Ca transport caused by dysfunction of the type 2 ryanodine receptor (RyR2) in the sarcoplasmic reticulum is associated with a variety of heart diseases, including catecholaminergic polymorphic ventricular tachycardia, atrial fibrillation, and HF." (PMID 33362553, 2020). "Both of them are regulators of RyR2 and mutations in both triadin and calmodulin have been associated with catecholaminergic polymorphic ventricular tachycardia, a rare familial arrhythmogenic disorder characterized by maligant ventricular arrhythmias and increased risk of SCD." (PMID 26196381, 2015). "The human ryanodine receptor 2 (RYR2) is one of the key players tightly regulating calcium efflux from the sarcoplasmic reticulum to the cytosol and found frequently mutated (<60%) in context of catecholaminergic polymorphic ventricular tachycardia (CPVT1)." (PMID 24978818, 2014). "Within the current decade, discovery of numerous RyR2 gene mutations which underlie the arrhythmogenesis that leads to sudden cardiac death (SCD) in catecholaminergic polymorphic ventricular tachycardia (CPVT), have added a new focus to the role of RyR2 dysfunction in cardiac disease." (PMID 19345240, 2009). "The dysfunction of RyR2 is linked to fatal cardiac arrhythmias, including heart failure (HF) and catecholaminergic polymorphic ventricular tachycardia (CPVT)." (PMID 41898308, 2026). "Mutations in RYR2 are well-known to be associated with various arrhythmias, specifically catecholaminergic polymorphic ventricular tachycardia (CPVT)." (PMID 40806606, 2025). "This study aimed to evaluate the safety of a nanoformulated siRNA developed to target the mutated cardiac Ryanodine Receptor gene (RyR2) that causes dominant catecholaminergic polymorphic ventricular tachycardia (CPVT)." (PMID 39860035, 2025). "Heterozygous autosomal-dominant single nucleotide variants in RYR2 account for 60% of cases of catecholaminergic polymorphic ventricular tachycardia (CPVT), an inherited arrhythmia disorder associated with high mortality rates." (PMID 38464671, 2024). "Mutations in the cardiac ryanodine receptor (RyR2) are associated with catecholaminergic polymorphic ventricular tachycardia (CPVT)." (PMID 39777228, 2024). "To date, around 350 missense mutations have been identified in RyR2, most linked with catecholaminergic polymorphic ventricular tachycardia (CPVT)." (PMID 39777228, 2024). "Heterozygous mutations in RYR2 cause cardiac arrhythmias including Catecholaminergic polymorphic ventricular tachycardia (CPVT) that are characterized by exercise-induced syncope, sudden cardiac arrest or sudden cardiac death." (PMID 38444585, 2024). "Genetic mutations have been identified in RyR2 and its multiple accessory proteins that cause a genetic arrhythmia syndrome called catecholaminergic polymorphic ventricular tachycardia (CPVT)." (PMID 36672139, 2023).
catecholaminergic polymorphic ventricular tachycardia (continued). "Another naturally occurring RyR2 mutation is responsible for catecholaminergic polymorphic ventricular tachycardia (CPVT) in humans, and myocytes from mouse hearts with the same mutation showed increased tendency for store overload induced Ca2+ release." (PMID 37122228, 2023). "Heterozygous missense variants of the cardiac ryanodine receptor gene (RYR2) cause catecholaminergic polymorphic ventricular tachycardia (CPVT)." (PMID 35439358, 2022). "Abnormal SR Ca2+ release due to missense mutations in RYR1 and RYR2 results in neuromuscular (e.g., malignant hyperthermia, MH) and cardiac disease (e.g., catecholaminergic polymorphic ventricular tachycardia, CPVT), respectively." (PMID 36311249, 2022). "RyR2 mutations have been associated with several cardiac conditions such as catecholaminergic polymorphic ventricular tachycardia (CPVT), sudden cardiac death, heart failure (HF), and other cardiac arrhythmias." (PMID 35677449, 2022). "Catecholaminergic polymorphic ventricular tachycardia (CPVT) is an arrhythmia syndrome caused by gene mutations that render RYR2 Ca release channels hyperactive, provoking spontaneous Ca release and delayed afterdepolarizations (DADs)." (PMID 34990403, 2022). "Many conditions, such as catecholaminergic polymorphic ventricular tachycardia (CPVT), heart failure (HF), and AF, have been linked to abnormal SR Ca2+ release and increased phosphorylation of the RyR2." (PMID 34831263, 2021). "The hereditary pro-arrhythmic condition catecholaminergic polymorphic ventricular tachycardia (CPVT), is associated with gene mutations involving ryanodine receptor type 2 (RYR2), calsequestrin (CASQ2), triadin (TRDN) or calmodulin (CALM1, CALM2 and CALM3)." (PMID 34643236, 2021). "Mutations in cardiac ryanodine receptor (RyR2) are linked to catecholaminergic polymorphic ventricular tachycardia (CPVT)." (PMID 33825858, 2021). "Cardiac ryanodine receptor (RyR2) mutations have been associated with catecholaminergic polymorphic ventricular tachycardia (CPVT), ventricular fibrillation (VF) and/or atrial fibrillation (AF)." (PMID 34440870, 2021). "Variants in the RYR2, encoding a ryanodine receptor, can cause catecholaminergic polymorphic ventricular tachycardia (CPVT), a fatal arrhythmia." (PMID 33562224, 2021). "It is also important to note that there may be sex differences in arrhythmogenic potentials secondary to underlying conditions, such as catecholaminergic polymorphic ventricular tachycardia (CPVT) associated with cardiac ryanodine receptor 2 (RyR2) mutations and other cardiac pathologies." (PMID 34501285, 2021). "For instance, RyR2 is oxidized in atrial tissue in vivo in a genetic model of catecholaminergic polymorphic ventricular tachycardia (CPVT), RyR2-R2474S+/− knockin mice, with increased susceptibility for pacing-induced atrial fibrillation." (PMID 34955889, 2021). "The first mutations found in the RyR2, were associated to catecholaminergic polymorphic ventricular tachycardia (CPVT)." (PMID 34725342, 2021). "Catecholaminergic Polymorphic Ventricular Tachycardia (CPVT) is a familial stress-induced arrhythmia syndrome, mostly caused by mutations in Ryanodine receptor 2 (RyR2), the sarcoplasmic reticulum (SR) Ca2+ release channel in cardiomyocytes." (PMID 34206855, 2021). "This has been especially emphasized by the fact that RyR2 mutations associated with catecholaminergic polymorphic ventricular tachycardia (CPVT) induced SAN dysfunction." (PMID 34690808, 2021). "To date, more than 150 mutations within RyR2 have been linked with catecholaminergic polymorphic ventricular tachycardia (CPVT)." (PMID 33790404, 2021). "Missense mutations in RYR2 were shown to be associated with catecholaminergic polymorphic ventricular tachycardia (CPVT), which is characterized by exercise-induced arrhythmias and sudden cardiac death." (PMID 33274235, 2020).
catecholaminergic polymorphic ventricular tachycardia (continued). "Studies have shown that mutations in RyR2 can cause catecholaminergic polymorphic ventricular tachycardia (CPVT), a heritable arrhythmogenic disease resulting in exertional syncope or sudden death." (PMID 31143551, 2019). "RYR2, encoding cardiac ryanodine receptor, is the major responsible gene for catecholaminergic polymorphic ventricular tachycardia (CPVT)." (PMID 30615235, 2019). "Recent experimental studies in transgenic mice carrying ryanodine receptor (RyR2) mutations, typically found in catecholaminergic polymorphic ventricular tachycardia (CPVT) patients, have demonstrated that the Ca‐dependent triggers of arrhythmia may originate in the Purkinje system." (PMID 31872561, 2019). "Leak is elevated in the failing heart, as well as in conditions characterized by gain-of-function mutations in proteins of the RyR2 macromolecular complex, such as catecholaminergic polymorphic ventricular tachycardia (CPVT)." (PMID 31091723, 2019). "Mutations in the cardiac ryanodine receptor (RYR2) are the leading cause for catecholaminergic polymorphic ventricular tachycardia (CPVT)." (PMID 29760739, 2018). "Catecholaminergic polymorphic ventricular tachycardia (CPVT) predisposes to ventricular arrhythmia due to altered Ca2+ homeostasis and can arise from ryanodine receptor (RyR2) mutations including RyR2-P2328S." (PMID 26545784, 2016). "Catecholaminergic polymorphic ventricular tachycardia (CPVT) is one of the causes of sudden cardiac death in young people and results from RYR2 mutations in ~60% of CPVT patients." (PMID 26114861, 2015). "Loss-of-function mutations of CASQ2 and RyR2 have been associated with catecholaminergic polymorphic ventricular tachycardia (CPVT), and CPVT patients often present with SAN bradycardia." (PMID 25863800, 2015). "In recent studies, S107, the RyR-specific derivative of JTV519, enhanced binding of FKBP12.6 to catecholaminergic polymorphic ventricular tachycardia (CPVT)-linked RyR2-R2474S mutant, and FKBP12 to the oxidized and hypernitrosylated RyR1." (PMID 23349825, 2013). "Catecholaminergic polymorphic ventricular tachycardia (CPVT) is a severe inherited cardiac disorder caused by mutations predominantly in the ryanodine receptor (RyR2) gene." (PMID 19216760, 2009). "The clinical spectrum of RyR2-related diseases (ryanodinopathy) has expanded beyond the well-established gain-of-function (GOF) mutations causing catecholaminergic polymorphic ventricular tachycardia (CPVT)." (PMID 42222672, 2026). "Abnormal regional variations in electrical and calcium homeostasis properties have been implicated in catecholaminergic polymorphic ventricular tachycardias (CPVT) attributable to abnormal RyR2-mediated store Ca2+ release, but their underlying mechanism have not been well explored in intact hearts." (PMID 39697246, 2024). "Notably, a RyR2 mutation (V4821I) in catecholaminergic polymorphic ventricular tachycardia (CPVT) was identified at the corresponding residue, V489247." (PMID 39294299, 2024). "A mouse model of CPVT (catecholaminergic polymorphic ventricular tachycardia) with highly oxidized RyR2 showed increased SR Ca2+ leak and propensity for AF." (PMID 37891912, 2023). "Targeted genetic testing includes the three genes linked to long QT syndrome (LQTS), namely KCNQ1, KCNH2, and SCN5A, the latter also causing Brugada syndrome (BrS), in addition to the RYR2 gene, which is linked to catecholaminergic polymorphic ventricular tachycardia (CPVT)." (PMID 36643077, 2023). "The RyR2-G4663S mutation, which is at the corresponding residue as the RyR1-G4733E, was reported to be associated with catecholaminergic polymorphic ventricular tachycardia (CPVT)." (PMID 38159862, 2023).
catecholaminergic polymorphic ventricular tachycardia (continued). "To date, two genetic diseases associated with mutations in ventricular RyR2 have been described: catecholaminergic polymorphic ventricular tachycardia (CPVT), or familial polymorphic ventricular tachycardia, and arrhythmogenic right ventricular cardiomyopathy/dysplasia (ARVC/D) type 2." (PMID 37958665, 2023). "In cardiac muscle, gain-of-function mutations in RYR2 and loss-of-function mutations in CASQ2 cause a similar phenotype, i.e. catecholaminergic polymorphic ventricular tachycardia (CPVT), which is caused by excessive SR Ca2+ leak." (PMID 36311237, 2022). "Catecholaminergic polymorphic ventricular tachycardia (CPVT) is a relatively rare inherited arrhythmic disease that causes sudden cardiac death, and is caused by mutations in the cardiac ryanodine receptor (RyR2) or sarcoplasmic reticulum protein calsequestrin 2 gene (CASQ2)." (PMID 36540835, 2022). "Naturally occurring mutations in RyR2 have frequently been associated with catecholaminergic polymorphic ventricular tachycardia (CPVT), but also with other phenotypes such as idiopathic ventricular fibrillation (IVF), atrial fibrillation (AF), and cardiomyopathies." (PMID 33825858, 2021). "RYR2 gene alterations are involved in the pathogenesis of catecholaminergic polymorphic ventricular tachycardia, familial atrial fibrillation, and cardiomyopathy." (PMID 33829027, 2021). "However, when extracardiac symptoms are atypical or absent, the patient can be diagnosed with Catecholaminergic Polymorphic Ventricular Tachycardia (CPVT), a rare arrhythmia at high risk of sudden death, mostly due to RYR2 mutations." (PMID 34899860, 2021). "Genetically modified murine RyR2-P2328S hearts modelling catecholaminergic polymorphic ventricular tachycardia (CPVT), recapitulated clinical ventricular and atrial pro-arrhythmic phenotypes following catecholaminergic challenge." (PMID 34643236, 2021). "A cardiac isoform of the ryanodine receptor does exist, RYR2, and mutations in this gene lead to a phenotype of catecholaminergic polymorphic ventricular tachycardia (CPVT) and a cardiomyopathy syndrome known as arrhythmogenic right ventricular dysplasia type 2 (ARVD2)." (PMID 34528764, 2021). "Catecholaminergic polymorphic ventricular tachycardia (CPVT) is a rare inherited arrhythmia syndrome characterized by adrenergically driven ventricular arrhythmia predominantly caused by pathogenic variants in the cardiac ryanodine receptor (RyR2)." (PMID 31994352, 2020). "This is particularly evident in catecholaminergic polymorphic ventricular tachycardia (CPVT), a genetic disorder characterized by mutations in the RyR2 macromolecular complex, whereby ventricular tachycardia and fibrillation (VT/VF) often only present in patients after exercise or stress." (PMID 32444920, 2020). "To assess how the approach described here could be applied to other genetic diseases, we analysed variants in RYR2 from a recently published referral cohort for catecholaminergic polymorphic ventricular tachycardia (CPVT)." (PMID 30696458, 2019). "The dual Na+ and cardiac Ca2+-release channel inhibitor, Flecainide (FLEC) is effective in patients with catecholaminergic polymorphic ventricular tachycardia (CPVT), a disease caused by mutations in cardiac Ca2+-release channels (RyR2), calsequestrin (Casq2), or calmodulin." (PMID 31456692, 2019). "This has also been recently demonstrated by an analysis of variation in the RYR2 gene in catecholaminergic polymorphic ventricular tachycardia." (PMID 30696458, 2019). "The present observations in Pgc-1β−/− hearts parallel features reported in Scn5a+/− and RyR2-P2328S/P2328S cardiac models for Brugada syndrome and catecholaminergic polymorphic ventricular tachycardia, respectively." (PMID 28821956, 2017). "Our data highlighted the predominant role of catecholaminergic polymorphic ventricular tachycardia and long QT syndrome, especially the RYR2 gene, as well as the minimal yield from other genes." (PMID 28449774, 2017).
catecholaminergic polymorphic ventricular tachycardia (continued). "Interestingly, catecholaminergic polymorphic ventricular tachycardia (CPVT) is caused by RyR2 mutation, and patients suffering from this condition are also prone to impaired glucose homeostasis and insulin secretion." (PMID 27642609, 2016). "In humans, single amino acid mutations in RyR2 lead to life-threatening cardiac arrhythmias, also as demonstrated by the ~160 mutations that have been linked so far to catecholaminergic polymorphic ventricular tachycardia (CPVT; Priori and Chen, 2011)." (PMID 24847270, 2014). "Mutation of RyR1 or RyR2 causes functional disorders of receptors and induces malignant hyperthermia, central core disease (CCD), catecholaminergic polymorphic ventricular tachycardia, and arrhythmogenic right ventricular dysplasia type 2." (PMID 24130701, 2013). "RYR2 mutations may cause catecholaminergic polymorphic ventricular tachycardia (CPVT) and arrhythmogenic right ventricular dysplasia (ARVD)." (PMID 23741331, 2013). "The variant NM_001035.3(RYR2):c.14302G>A in sample 4 was previously discussed in the literature and classified as a VUS specifically involved in cardiac disease, such as cardiomyopathy and catecholaminergic polymorphic ventricular tachycardia (CPVT)." (PMID 41300725, 2025). "While CALM mutations have been primarily associated with early-onset syndromes such as catecholaminergic polymorphic ventricular tachycardia (CPVT) and long QT syndrome (LQTS) through dysregulation of RyR2 and CaV1.2, recent evidence suggests an expanded phenotypic spectrum." (PMID 40722809, 2025). "Catecholaminergic polymorphic ventricular tachycardia (CPVT) is a highly arrhythmogenic syndrome triggered by stress, primarily linked to gain-of-function point mutations in the cardiac ryanodine receptor (RyR2)." (PMID 39796059, 2024). "Additionally, flecainide was reported to block calcium release channel, ryanodine receptor-2 (RyR2), and thereby suppress calcium waves in cardiomyocytes and prevent catecholaminergic polymorphic ventricular tachycardia in mice and humans." (PMID 37696662, 2023). "Although several LQTS-related variants on RYR2 have been reported, a considerable part of RYR2 variants are shared with other cardiac diseases, and it is particularly considered as a causative gene for catecholaminergic polymorphic ventricular tachycardia (CPVT)." (PMID 36480497, 2022). "Also, variants were detected in ryanodine receptor 2 (RYR2), a gene associated with both cardiomyopathies and catecholaminergic polymorphic ventricular tachycardias." (PMID 35087879, 2021). "SCN5A genetic alterations are present in 30% of all Brugada syndrome cases while the RYR2 genetic alterations are reported because of catecholaminergic polymorphic ventricular tachycardia, atrial fibrillation, and arrhythmogenic right ventricular cardiomyopathy." (PMID 33829027, 2021). "Abnormal Ca2+ release is the driving force for arrhythmia observed in patients with catecholaminergic polymorphic ventricular tachycardia (CPVT), a condition characterized by pathogenic mutations in RyR2, as well as in associated accessory proteins including CSQ." (PMID 30425651, 2018). "This patient had also a novel homozygous mutation in ryanodine receptor 2 (RYR2) in position c.365G>A (p.R122H), but no clear Catecholaminergic Polymorphic Ventricular Tachycardia (CPVT) was observed." (PMID 29568272, 2018).